PTPRN (protein tyrosine phosphatase receptor type N)
Description:
Plays a role in vesicle-mediated secretory processes. Required for normal accumulation of secretory vesicles in hippocampus, pituitary and pancreatic islets (By similarity). Required for the accumulation of normal levels of insulin-containing vesicles and preventing their degradation. Plays a role in insulin secretion in response to glucose stimuli. Required for normal accumulation of the neurotransmitters norepinephrine, dopamine and serotonin in the brain (By similarity). In females, but not in males, required for normal accumulation and secretion of pituitary hormones, such as luteinizing hormone (LH) and follicle-stimulating hormone (FSH) (By similarity). Required to maintain normal levels of renin expression and renin release (By similarity). Seems to lack intrinsic enzyme activity (By similarity). May regulate catalytic active protein-tyrosine phosphatases such as PTPRA through dimerization (By similarity). [ICA512-transmembrane fragment]: ICA512-TMF regulates dynamics and exocytosis of insulin secretory granules (SGs); binding of ICA512-TMF to SNTB2/beta-2-syntrophin is proposed to restrain SGs mobility and exocytosis by tethering them to the actin cytoskeleton depending on UTRN; the function is inhibited by cytoplasmic ICA512-CFF dimerizing with ICA512-TMF and displacing SNTB2. [ICA512-cleaved cytosolic fragment]: ICA512-CCF translocated to the nucleus promotes expression of insulin and other granule-related genes; the function implicates binding to and regulating activity of STAT5B probably by preventing its dephosphorylation and potentially by inducing its sumoylation by recruiting PIAS4. Enhances pancreatic beta-cell proliferation by converging with signaling by STAT5B and STAT3. ICA512-CCF located in the cytoplasm regulates dynamics and exocytosis of insulin secretory granules (SGs) by dimerizing with ICA512-TMF and displacing SNTB2 thus enhancing SGs mobility and exocytosis.
Synonyms: R-PTP-N; ICA512; IA-2; IA-2/PTP; IA2
Tractability: Small molecule: it has a high-quality binding pocket. Antibody: UniProt places it where antibodies can reach, with high confidence; UniProt predicts a signal peptide or a membrane-spanning region; its Gene Ontology location is reachable by antibodies, with medium confidence. PROTAC: UniProt records ubiquitination sites on it.
Gene: Protein-coding gene on chromosome 2 (219,289,623 to 219,309,648, reverse strand). Ensembl gene ENSG00000054356.
Subcellular location: Membrane; Cytoplasmic vesicle, secretory vesicle membrane; Perikaryon; Cell projection, axon; Synapse; Cell membrane; Endosome; Cytoplasmic vesicle, secretory vesicle membrane (ICA512-transmembrane fragment); Nucleus (ICA512-cleaved cytosolic fragment)
Subcellular location (Human Protein Atlas): Endoplasmic reticulum
Gene Ontology:
Molecular function: protein binding; spectrin binding; transcription factor binding; ubiquitin-like protein ligase binding
Biological process: dense core granule maturation; insulin secretion; positive regulation of transcription by RNA polymerase II; positive regulation of type B pancreatic cell proliferation; response to reactive oxygen species; insulin secretion involved in cellular response to glucose stimulus; luteinization; regulation of secretion
Cellular component: nucleus; plasma membrane; axon terminus; endosome; Golgi apparatus; membrane; neuronal cell body; perikaryon; secretory granule; synapse; synaptic vesicle; axon; transport vesicle membrane
Genetic constraint (gnomAD): Loss-of-function variants: 70 observed, 109.83 expected, observed/expected ratio (o/e) 0.64, 90% interval 0.52 to 0.78. The upper end of that interval is the gene's LOEUF score, 0.78, which puts it in group 3 of 6, group 1 being the genes least tolerant of losing a copy. Missense variants: 1,136 observed, 1,312.8 expected, observed/expected ratio (o/e) 0.87, 90% interval 0.82 to 0.91. Synonymous variants: 495 observed, 533.95 expected, observed/expected ratio (o/e) 0.93, 90% interval 0.86 to 1.
Homologues: Orthologues: chimpanzee PTPRN (99% identical), macaque PTPRN (97% identical), pig PTPRN (92% identical), dog PTPRN (91% identical), rabbit PTPRN (91% identical), mouse Ptprn (87% identical), guinea pig PTPRN (86% identical), rat Ptprn (85% identical), tropical clawed frog ptprn (54% identical), zebrafish ptprna (49% identical), zebrafish ptprnb (47% identical). Paralogues in human: PTPRN2 (42% identical), PTPRF (20% identical), PTPRB (19% identical), PTPRS (19% identical), PTPRD (19% identical), PTPRK (17% identical), PTPN13 (17% identical), PTPRM (17% identical), PTPRZ1 (17% identical), PTPRT (16% identical), PTPN23 (16% identical), PTPRU (16% identical), and 23 more.
Diseases named in the same sentence as PTPRN in open-access papers:
PTPRN is named in the same sentence as 70 diseases in open-access papers, as found by Europe PMC text mining. Sharing a sentence is not in itself a finding about the gene and the disease. The quoted sentences say what the papers report.
type 1 diabetes (72 papers, 2003 to 2026). "PTPRN encodes islet antigen 2 (IA-2), a major type 1 diabetes autoantigen involved in glucose-stimulated insulin secretion." (PMID 35763030, 2022). "As a member of protein tyrosine phosphatase (PTP), PTPRN is an autoantigen in the sera of insulin-dependent diabetes mellitus (IDDM) patients, making it a promising therapeutic target of autoimmunity in IDDM." (PMID 29915691, 2018). "Despite encoding a major type I diabetes autoantigen and given its impact on insulin secretion, not a single PTPRN polymorphism has been unambiguously linked to neuroendocrine diseases." (PMID 36755664, 2022). "The chronic autoimmune reaction in type 1 diabetes is directed towards specific beta cell antigens, which include the beta cell surface proteins insulin, PTPRN (which is also known as insulinoma antigen 2 or IA-2) and zinc transporter 8 (also referred to as ZNT8 or SLC30A8)." (PMID 22460761, 2012). "The anti-PTPRN scFv developed in this study could be introduced as an effective tool that can pave the way for the creation of antibody-based targeting systems in cooperation with the detection and therapy of type I diabetes." (PMID 38355744, 2024). "Phogrin (IA-2β or PTPRN2) and IA-2 (PTPRN or ICA512), autoantigens in insulin-dependent diabetes, are type 1 transmembrane proteins belonging to the IA-2 family of protein-tyrosine phosphatase (PTP)." (PMID 38201998, 2024). "Therefore, the result of the present study, the development of scFv against PTPRN as pancreatic beta cells, could be used for the generation of CAR-T reg cells for type I diabetes in future works." (PMID 38355744, 2024). "PTPRN and PTPRN2 are both expressed in neuro-endocrine cells and proteolytic processing of their products yields protein fragments that represent major autoantigens in type 1 diabetes and are critical regulators of endocrine secretion in adrenal, pancreatic and brain tissue." (PMID 36755664, 2022).
diabetes (71 papers, 2003 to 2025). "We also found increases in the diabetes-associated Islet-cell autoantigen PTPRN, a 60-kDa type 1 membrane protein associated with the pancreatic and adrenal DCSVs together with Chromogranin B, a master regulator of DCSV biogenesis and function." (PMID 33711921, 2021). "PTPRN has been identified as an autoantigen that reacts with insulin-dependent diabetes mellitus (IDDM) patient sera." (PMID 35873480, 2022). "Diabetes-related gene screening experiments indicated that PTPRN plays an important role in occurrence and development of diabetes mellitus." (PMID 34557405, 2021). "The top diabetes-related antigens were GAD, insulin, IA-2/PTPRN, IGRP, ZnT8, HSP, and ICA-1, representing nearly 90% of the captured data." (PMID 25140192, 2013).
glioma (9 papers, 2021 to 2026). A benign or malignant brain and spinal cord tumor that arises from glial cells (astrocytes, oligodendrocytes, ependymal cells). "In low‐grade gliomas, PTPRN has been proposed as a prognostic marker linked to immune infiltration, whereas high PTPRN expression correlates with poor outcomes in high‐grade glioma." (PMID 41543046, 2026). "The results of the present study indicated that a low level of PTPRN was associated with an improved prognosis in glioma patients." (PMID 34557405, 2021). "Among the chemotherapeutic drugs, cisplatin and erlotinib had a significantly good treatment effect for glioma with expression of PTPRN or RIM-BP2 and in lower-grade glioma (LGG) with IDH mutation." (PMID 34976783, 2021). "PTPRN expression, which negatively regulates immune cell infiltration in low grade glioma, is correlated with a favorable prognosis of patients." (PMID 36713370, 2022). "Kaplan-Meier analysis showed that high expression levels of PTPRN correlated with a good overall survival (OS) of patients with glioma (p = 0.000)." (PMID 35741647, 2022). "Univariate analysis showed that the level of PTPRN, MGMT, VEGF and WHO grade were associated with the prognosis of glioma patients." (PMID 34557405, 2021). "Survival analysis of PTPRN expression based on the TCGA database showed that high expression of PTPRN indicated a poor prognosis of high-grade glioma." (PMID 34557405, 2021). "PTPRN downregulation reduced the proliferation and migration of glioma cells, and PTPRN overexpression induced the proliferation and migration of glioma cells." (PMID 34557405, 2021). "To clarify the mechanism of action of PTPRN in glioma cells, we downregulated PTPRN, detected the changes in the pathways in glioma cells, and determined possible factors related to PTPRN that influenced the changes in the pathways." (PMID 34557405, 2021). "We analysed the prognosis of glioma patients and observed the effect of PTPRN on the phenotype of glioma cells." (PMID 34557405, 2021). "Furthermore, knockout of Ptprn has been reported to reduce, whereas overexpression of PTPRN increases proliferation and migration of glioma cells." (PMID 39926347, 2025). "Additionally, PTPRN expression was significantly higher in IDH mutation status (p = 0.000) and 1p/19q codeletion status gliomas (p = 0.000)." (PMID 35741647, 2022). "Therefore, additional research in vitro and in vivo is needed to confirm PTPRN efficacy as a viable target in the glioma immune microenvironment and to develop glioma immunotherapy in the future." (PMID 35741647, 2022). "Interestingly, PTPRN is highly expressed in patients with high-grade glioma, which activates the PI3K/AKT pathway by interacting with HSP90AA1 to promote cell proliferation and metastasis." (PMID 35741647, 2022). "Reducing the expression of PTPRN in glioma cells can be used as a potential therapeutic strategy." (PMID 34557405, 2021). "RNA-seq was conducted to confirm the pathways that played a role in PTPRN functions in glioma." (PMID 34557405, 2021). "We further analyzed whether the current treatment options for GBM, including RT and chemotherapy, are beneficial even when the PTPRN or RIM-BP2 expression in glioma is abnormal." (PMID 34976783, 2021). "The result showed that High expression of PTPRN indicated a poor prognosis of high-grade glioma." (PMID 34557405, 2021). "The glioma stem cell frequency was decreased in the PTPRN knockdown group." (PMID 34557405, 2021). "Treatment with BEZ235 reversed the growth and migration of PTPRN-overexpressing U251 glioma cells." (PMID 34557405, 2021). "Effect of PTPRN knockdown on the transcriptome was studied in U87 glioma cells." (PMID 34557405, 2021). "The glioma stem cell frequency was decreased in the PTPRN overexpression group." (PMID 34557405, 2021). "However, the expression of PTPRN was similar in different grades of glioma (p = 0.101)." (PMID 35741647, 2022).
glioma (continued). "Thus, we suggest that glioma patients with high expression of PTPRN have a poor prognosis." (PMID 34557405, 2021). "Moreover, the expression of PTPRN was an independent factor for the prognosis of glioma patients." (PMID 34557405, 2021). "Interestingly, we explored the mechanism by which PTPRN functions in glioma cells." (PMID 34557405, 2021). "consistently showed that PTPRN interacts with HSP90AA1 to activate PI3K/AKT signaling pathway and promote the proliferation and metastasis of high-grade gliomas." (PMID 36814929, 2023). "These study showed that PTPRN may play an important role in the occurrence and development of glioma; however, at present, there are no relevant experimental studies of PTPRN in vivo or in vitro in glioma." (PMID 34557405, 2021).
glioblastoma (5 papers, 2018 to 2022). The most malignant astrocytic tumor (WHO grade IV). "PTPRN is a transmembrane protein and is expressed in different tumors, including breast cancer, hepatocellular carcinoma, ovarian cancer, and glioblastoma." (PMID 35741647, 2022). "PTPRN was overexpressed in a group of glioblastoma patients, indicating poor survival." (PMID 35741647, 2022). "PTPRN was overexpressed in a cluster of glioblastoma patients and indicated poor survival." (PMID 34150744, 2021). "Besides, PTPRN was reported to be overexpressed in several cancers such as glioblastoma and hepatocellular carcinoma." (PMID 34150744, 2021). "Furthermore, PTPRN could be a biomarker that predicts the prognosis of glioblastoma and could estimate the OS of patients with glioblastoma." (PMID 35741647, 2022). "However, MED10 and PTPRN have not been previously reported in glioblastoma-related studies." (PMID 30382873, 2018). "We used data from the GEO and TCGA databases and identified five genes (ITGA5, MMP9, PTPRN, PTX3, and STX1A) that could affect the survival rate of glioblastoma patients and that were differentially expressed between glioblastoma patients and non-tumors groups." (PMID 33767729, 2021).
lung adenocarcinoma (5 papers, 2021 to 2026). A carcinoma that arises from the lung and is characterized by the presence of malignant glandular epithelial cells. "In lung adenocarcinoma, the elevated metastasis ability and decreased NK cell activity were identified to be associated with PTPRN overexpression." (PMID 34862763, 2022). "As shown in a previous study, high expression of PTPRN inhibits NK cell cytotoxicity and promotes lung adenocarcinoma metastasis." (PMID 41543046, 2026). "The negative regulation between PTPRN expression and immune response as well as immune cells was also observed in lung adenocarcinoma." (PMID 36713370, 2022). "PTPRN was upregulated in lung adenocarcinoma (LUAD) and promotes metastasis and poor prognosis." (PMID 41295383, 2025). "Lung adenocarcinoma (LUAD) is the most common diagnostic histologic subtype of non-small cell lung cancer, but the role of receptor-type tyrosine-protein phosphatase-like N (PTPRN) in LUAD has not been studied." (PMID 34150744, 2021).
hepatocellular carcinoma (3 papers, 2019 to 2022). A malignant tumor that arises from hepatocytes. "PTPRN has been confirmed to be negatively related to the survival of hepatocellular carcinoma patients and closely related to liver tumorigenesis." (PMID 31130992, 2019). "PTPRN was identified as an independent prognostic factor in hepatocellular carcinoma." (PMID 35741647, 2022). "PTPRN was also an independent prognostic factor of hepatocellular carcinoma." (PMID 34150744, 2021).
ovarian carcinoma (3 papers, 2018 to 2022). A malignant neoplasm originating from the surface ovarian epithelium. "Moreover, the hypermethylation of PTPRN is also associated with shorter survival in ovarian cancer patients." (PMID 31130992, 2019). "Hypermethylation in PTPRN was associated with longer progression-free survival in ovarian cancer." (PMID 29915691, 2018).
small cell lung carcinoma (3 papers, 2009 to 2020). Small cell lung cancer (SCLC) is a highly aggressive malignant neoplasm, accounting for 10-15% of lung cancer cases, characterized byrapid growth, and early metastasis. "A high expression of PTPRN in small cell lung cancer is associated with tumor growth and proliferation." (PMID 31130992, 2019).
breast carcinoma (2 papers, 2021 to 2022). "In addition, the expression of PTPRN mRNA and protein increased in breast cancer cells under hypoxia." (PMID 35741647, 2022). "PTPRN is abnormally expressed in many tumors, including small cell lung cancer (SCLC), breast cancer, and liver cancer, and affects tumor progression." (PMID 34976783, 2021).
colorectal cancer (2 papers, 2025 to 2026). A primary or metastatic malignant neoplasm that affects the colon or rectum. "This study aimed to investigate the role of TMEM59L in regulating PTPRN‐mediated DNA damage repair and its impact on 5‐FU sensitivity in colorectal cancer, with the goal of identifying potential therapeutic targets to overcome chemoresistance." (PMID 41543046, 2026). "In colorectal cancer, PTPRN deletion impairs invasiveness and metastatic potential through dysregulated epithelial–mesenchymal transition (EMT) and insulin receptor signaling." (PMID 41295383, 2025).
Alzheimer disease (1 paper, 2019). A progressive, neurodegenerative disease characterized by loss of function and death of nerve cells in several areas of the brain leading to loss of cognitive function such as memory and language. "PTPRN is expressed in neurons and PTPRN levels are reported to be depressed in Alzheimer’s disease patients." (PMID 31487305, 2019).
astrocytoma (1 paper, 2022). "In our study, we found that PTPRN expression was significantly lower in astrocytoma than in oligodendrocytoma, which again confirmed the prognostic value of PTPRN expression." (PMID 35741647, 2022). "In oligodendroglioma, PTPRN expression was sharply higher than astrocytoma (p = 0.000)." (PMID 35741647, 2022).
breast tumors (1 paper, 2022). "We found that 3 (PTPRN, HIST1H2BH, and HIST1H2AM mRNAs) of 60 upregulated genes in breast tumors of patients ≤40 years were also upregulated in normal breast tissues in the luteal phase." (PMID 35741056, 2022).
epilepsy (1 paper, 2024). A brain disorder characterized by episodes of abnormally increased neuronal discharge resulting in transient episodes of sensory or motor neurological dysfunction, or psychic dysfunction. "Consistent with the normal course of epilepsy in this model, the latency between SE termination and the first spontaneous seizure averaged 13.5 days in PTPRN‐WT mice (13.55 ± 0.34 days)." (PMID 38874331, 2024). "We also observed enhanced PTPRN expression in two animal models of epilepsy." (PMID 38874331, 2024). "In addition, PTPRN‐KO mice showed higher mortality in the latent period of epilepsy after induction of SE." (PMID 38874331, 2024). "Given the involvement of NaV1.2 channels in various neurological and psychiatric brain disorders beyond epilepsy, our results suggest that modulating intrinsic neuronal excitability via the PTPRN‐NaV1.2 axis could play a significant role in both physiological and pathological processes of the brain." (PMID 38874331, 2024). "Because epilepsy is characterized by recurrent spontaneous seizures due to the hyperexcitability and hypersynchrony of brain neurons, we further investigated whether PTPRN expression responds to neural activities." (PMID 38874331, 2024).
Hyperinsulinemia (1 paper, 2021). An increased concentration of insulin in the blood. "Functional deletion of PTPRN (IA-2) in mice results in impaired secretion of insulin, whereas overexpression leads to an increase in DCSVs and insulin secretion, which may have contributed to the hyperinsulinemia that we and others have observed in the KK/HlJ strain." (PMID 33711921, 2021).
low grade glioma (1 paper, 2022). A grade I or grade II glioma arising from the central nervous system. "Among the hub genes, PTPRN expression was reported to significantly restraint the infiltrating levels of CD4 T cells, B cells, macrophages, neutrophil, and dendritic cells in low grade glioma." (PMID 36713370, 2022).